TTC14 (tetratricopeptide repeat domain 14)
Synonyms: KIAA1980; FLJ00166; DRDL5813; PRO19630
Tractability: PROTAC: UniProt records ubiquitination sites on it; ubiquitination databases record sites on it; its protein half-life has been measured.
Gene: Protein-coding gene on chromosome 3 (180,602,163 to 180,617,828, forward strand). Ensembl gene ENSG00000163728.
Subcellular location (Human Protein Atlas): Nucleoplasm
Gene Ontology:
Molecular function: nucleic acid binding
Genetic constraint (gnomAD): Loss-of-function variants: 67 observed, 82.1 expected, observed/expected ratio (o/e) 0.82, 90% interval 0.67 to 1. The upper end of that interval is the gene's LOEUF score, 1, which puts it in group 4 of 6, group 1 being the genes least tolerant of losing a copy. Missense variants: 895 observed, 920.64 expected, observed/expected ratio (o/e) 0.97, 90% interval 0.92 to 1.03. Synonymous variants: 335 observed, 316.72 expected, observed/expected ratio (o/e) 1.06, 90% interval 0.97 to 1.16.
Homologues: Orthologues: chimpanzee TTC14 (99% identical), macaque TTC14 (99% identical), rabbit TTC14 (93% identical), pig TTC14 (92% identical), guinea pig TTC14 (91% identical), dog TTC14 (91% identical), mouse Ttc14 (87% identical), rat Ttc14 (87% identical), tropical clawed frog ttc14 (56% identical), zebrafish ttc14 (49% identical), Drosophila melanogaster CG6621 (27% identical).
Diseases named in the same sentence as TTC14 in open-access papers:
TTC14 is named in the same sentence as 1 disease in open-access papers, as found by Europe PMC text mining. Sharing a sentence is not in itself a finding about the gene and the disease. The quoted sentences say what the papers report.
ductal carcinomas (1 paper, 2007). "The genes encoding proteins involved in ubiquitin-mediated proteolysis, such as USP3, RKHD2 and TTC3, and nuclear components, such as DTL, GLCC11, TTC14, FAM54A, HIST1H3B, were upregulated in ductal carcinomas." (PMID 17389037, 2007).